IL18 (interleukin 18)
Diseases named in the same sentence as IL18 in open-access papers (continued):
Sharing a sentence is not in itself a finding about the gene and the disease.
infection (continued). "In the stomach, IL18 expression is constitutive but is upregulated in response to infection by the pathogenic bacterium, H. pylori." (PMID 37365163, 2023). "Transcript levels of IL-18 and IL-1β were significantly increased in liver tissues after WT W24 infection, and this consequence was similar to that caused by LPS injection." (PMID 36977062, 2023). "Studies have shown that IL-18 deficiency was associated with higher parasitic burden in later stage i.e. 40–44 days post-infection, in comparison with uninfected mice." (PMID 36002553, 2022). "IL-1 has been associated with the host response during UPEC mediated infection, but IL-18 and IL-33 currently lack a known role in the host response during UPEC infection." (PMID 35132157, 2022). "The vital role played by IL-18 in establishing NK cell activity has been demonstrated in IL-18 deficient mice, which have increased susceptibility to infection and impaired NK cell activity." (PMID 36032110, 2022). "IL-1β is a potent proinflammatory mediator implicated in recruiting immune cells to the site of infection and stimulating adaptive immune responses, and IL-18 induces the sequential activation of natural killer cells and cytotoxic T cells." (PMID 34943932, 2021). "Inflammasome activation leads to the release of IL-18, and mice that lack IL-18 are more susceptible to infection." (PMID 33372132, 2021). "NLRP3 inflammasomes respond to various risk states of the body (including infection and metabolic disorders) after inflammatory factors (IL-1β, IL-18) are released, mainly causing lung injury." (PMID 33954183, 2021). "The experiments revealed that a signaling molecule called type I interferon, which is thought to be antiviral, causes neutrophils at the site of the infection to produce proteins, such as IL-18, which trigger an inflammatory reaction." (PMID 34047696, 2021). "In the context of infection, inflammasome-mediated cell death pathways and IL-18 secretion have been implicated in this epithelial-intrinsic response." (PMID 32330185, 2020). "The intravenous infection of IL-18-deficient mice (IL-18−/−) with P. brasiliensis yeast cells resulted in a higher fungal burden in the lungs compared with wild-type (WT) animals and absence of granuloma formation." (PMID 33117339, 2020). "Inflammasomes are formed in response to danger signals, associated with infection and injury, and mainly regulate the secretion of interleukin-1β and interleukin-18." (PMID 33143375, 2020). "Studies show an association of IL18-607 C/A SNP (rs1946518) with protection or risk in several infections." (PMID 33117339, 2020). "IL-18 is a susceptibility factor in CL since IL-18-/- mice control infection compared to WT C57BL/6 mice." (PMID 33415318, 2020). "Our results corroborate the importance of IL-18 as a determinant of infection susceptibility and reveal a previously unappreciated pathway for IL-18 regulation via vitamin A signaling and dietary vitamin A." (PMID 32330185, 2020). "Inflammatory monocytes recruited by chemokine CCL3 produced in the intestinal mucosa by ICLs cells in dependence upon IL-18 in the intestine are associated with the ability to suppress early parasite replication at the site of infection." (PMID 33324583, 2020). "Resistance to primary infection with herpes simplex virus 2 (HSV-2) was attenuated in IL-18-deficient mice or anti-IL-18 antibody treated mice, and the survival rate was reduced after infection." (PMID 30717382, 2019). "Fas−/− mice were highly susceptible to Listeria monocytogenes, an intracellular Gram-positive bacterium that causes serious food-born infections in humans, with the impaired secretion of IL-18 and IL-1β." (PMID 30717382, 2019). "Although the genes encoding the pro-inflammatory cytokines such as IL-18 were up-regulated in submandibular LN, the overall inflammatory response was putatively suppressed during the early phase of infection." (PMID 30789917, 2019).
infection (continued). "Concerning genetic control of the infection, our results evidenced the implication of the IL18 rs360719 polymorphism, in our populations." (PMID 31751351, 2019). "The significant production of pro-inflammatory cytokine IL-1β after VSV or EMCV infection was further confirmed by enzyme-linked immunosorbent assays (ELISA) as well as the secretion of IL-18." (PMID 31024004, 2019). "Epithelium-derived IL-18 has also been implicated in protecting against infection-associated intestinal inflammation." (PMID 28979266, 2017). "For example, IL-18-deficient or IL-18R-deficient mice were more susceptible to colonization and inflammation upon infection with C. rodentium." (PMID 28979266, 2017). "Little is known regarding IL-18 levels in HTLV-1 infection but polymorphisms in the IL-18 promoter have been associated with susceptibility to infection." (PMID 28384290, 2017). "This control was associated with IL-1β and IL-18 secretion induced by caspase-1 activity starting at an early phase of infection." (PMID 28740491, 2017). "Others have reported the activation of NLRP3 complexes and recruitment of caspase-1, together with IL-18/IL-1β release, in primary microglia and in macrophages stimulated by infection-associated agents." (PMID 28096568, 2016). "A recent study examined intranasal Ft LVS infection of IL-1-/- and IL-18-/- mice, revealing increased susceptibility of IL-18 deficient mice and a critical role for IL-1β in the early production of protective anti-Ft LPS IgM by B1a B cells." (PMID 27926940, 2016). "To verify this in our infection model, we infected IFNγ- and IL-18-deficient mice for 72h with S.Tm, a time point when the pathogen has spread from the mucosal tissue to systemic organs." (PMID 27341123, 2016). "The influence of IL18 gene variants on the susceptibility to infection or severity of other protozoan infectious diseases has been also evaluated." (PMID 27027876, 2016). "After Ft LVS infection IL-1β and IL-18 levels are similar between Aim2- and Nlrp3-deficient mice, yet mice deficient in Aim2, ASC, or caspase-1/11 do not reproduce the survival phenotype of Nlrp3 mice." (PMID 27926940, 2016). "Infection of macaques with simian/human immunodeficiency viruses resulted in a transient increase in IL-18 serum levels at primary viremia and elevated IL-18 production was associated with seroconversion." (PMID 27821119, 2016). "In conclusion, our results suggest that IL18 variation plays an important role in the susceptibility to infection by T. cruzi, probably by influencing IL-18 production during the immune response in the early stages of the infection." (PMID 27027876, 2016). "Some studies have shown a positive role for IL-18 through the amplification of Th1 responses, but others have shown a potential for biasing Th2 responses and infection susceptibility." (PMID 27009263, 2016). "Mice deficient in IL-18 quickly succumbed to the infection but administration of IFNγ rescued their survival." (PMID 25768794, 2015). "The studies described here analyzed for the first time the response of IL-1- or IL-18-deficient mice to intranasal infection with Ft LVS." (PMID 25768794, 2015). "Peg-IFNα-based dual therapy caused distinct increases in levels of sCD14 and IL-18, and these effects were stronger in patients whom went on to clear the infection." (PMID 25166593, 2014). "IL-18 is upregulated in response to C. parvum infection, and exogenous IL-18 significantly decreased parasite load while IL-18 knockout mice are susceptible to infection." (PMID 22685452, 2012). "Remarkably, despite the abundance of IL-1β and IL-18, Nlrc4-/- mice were dramatically more susceptible to melioidosis than WT mice, rapidly succumbed to the infection, and had very high organ's bacteria burden and worst neutrophilic lung inflammation." (PMID 22241982, 2011).
infection (continued). "Screenings for possible insert specific effects examined IL-10, IL-12 and IL-18 which have been implicated as protective during infection by intracellular pathogens." (PMID 20642814, 2010). "Several polymorphisms in the IL-18 gene are known, and at least one SNP (IL18 C607A) has been associated with increased risk of infection in a pediatric cohort." (PMID 17651505, 2007). "Furthermore, IL-18 deficiency also results in increased susceptibility to infection with the dermotropic species L. amazonensis, suggesting that IL-18-mediated protection extends beyond viscerotropic parasites." (PMID 40794782, 2025). "Importantly, inflammasome-mediated secretion of IL18 is harmful for the host, as mice deficient in the IL18 receptor are more resistant to fatal infection and have a lower bacterial burden and reduced inflammation." (PMID 41204030, 2025). "In WT animals, P21 infection caused an exacerbated inflammatory response characterized by high viral loads, weight loss, lung pathology and a significant increase in pro-inflammatory cytokines in the lungs, including IL-1β and IL-18." (PMID 38286985, 2024). "Our work also finds an important role of IL18 in Tfh differentiation, suggesting that the use of systemic strategies to block IL18 may increase the risk of fatal infection due to the risk of reduced Tfh cells and antibody production." (PMID 38381113, 2024). "Thus, we quantified inflammasome-associated cytokines, IL-1β and IL-18, in cecal and colonic tissues of the infected mice during the first 4 days of the infection." (PMID 39298531, 2024). "Infection led to a similar loss of cecal goblet cells (i.e. depletion) in Il18−/− and WT mice, however the goblet cells remaining in the Il18−/− mice were significantly larger (mean diameter of 9.32 μm) than those in their WT littermates (mean diameter of 6.84 μm)." (PMID 39428744, 2024). "High levels of IL18 might contribute to the more severe tissue damage caused by the highly virulent strains in later stages of infection." (PMID 36544767, 2022). "In contrast, GSDMD deficiency would inhibit the release of IL-1β and IL-18 after the infection." (PMID 36311722, 2022). "The recently described “all-in-one” lentiviral vector encoding constitutive GD2 CAR and inducible IL-18 expression was used for cell transduction on day 1 of the manufacturing process with a multiplicity of infection (MOI) of 29 for D1 and 10 for D2 derived T cells." (PMID 35401506, 2022). "Likewise, the levels of pro-inflammatory cytokines implicated in CA16 infection, namely, IL-1β, IL-6, IL-18, and IFN-γ, were found to be significantly elevated in infected hSCARB2 transgenic mice." (PMID 33882964, 2021). "Furthermore, we suggest that extrinsic and intrinsic apoptosis caused by MO infection are associated with increased expression of proinflammatory cytokines, including IL-1β, IL18, and TNF-α." (PMID 34678131, 2021). "Here, we detected an IL-18 signaling signature with higher amount of phosphorylation linked to progression (pATF2, pAKT, pNF-kB) and de-repression of the cell cycle (pFOXO3A) during the acute phase of the infection." (PMID 31467285, 2019). "The natural immune response that occurs as an early response to infection causes the release of proinflammatory cytokines such as interleukin 1, interleukin beta, and interleukin 18 from macrophages in the cytoplasm, which in turn induce caspase-1-dependent cell death." (PMID 31245979, 2019). "This prominent feature of IL-18 might explain the mechanism for infection-associated allergic diseases." (PMID 30717382, 2019). "Indeed, IL-18-deficient C57BL/6 mice had a severe infection and pathological changes that were significantly suppressed by treatment with exogenous IL-18." (PMID 30717382, 2019). "Since chMIF was secreted by DT40 and bursal cells upon vvIBDV infection, we also investigated whether the supernatant of the infected cells could cause upregulation of IL-1β and IL-18 in response to vvIBDV infection." (PMID 31632367, 2019).
infection (continued). "In addition, differences in host susceptibility to IL-1β, IL-18, and caspase-1-deficient mice during infection have been reported." (PMID 29616195, 2018). "Indeed, the progressive infection in rhesus macaques is associated with production of IL-15, IL-18, IFN-γ, granulocyte-colony stimulating factor (G-CSF), MCP-1 and macrophage inflammatory protein (MIP)-1β but not in non-progressive sooty mangabeys." (PMID 30568659, 2018). "In lymph nodes that drain infected tissues, prompt lymphocyte-macrophage communication, involving rapid production of IFNγ from resident lymphocytes and release of interleukin-18 from proximally associated macrophages, is crucial to limit the spread of infection." (PMID 28830544, 2017). "Hence, large intestinal IL-6 secretion as well as TNF and IL-18 mRNA levels were higher in NOD2−/− as compared to WT mice upon pathogenic infection, whereas C. jejuni induced colonic IL-22 down-regulation occurred in WT mice only." (PMID 28127403, 2017). "Consequently, AP-3 deficient DCs hyposecrete IL-1β and IL-18 in response to phagocytosed stimuli, and AP-3 deficient mice succumb to infection by a bacterial pathogen." (PMID 29253868, 2017). "However, mice deficient for IL-1β, IL-18 or caspase 1 were as susceptible as wild-type mice to both blood stage and sporozoite PbA-infection." (PMID 28448579, 2017). "Indeed, following infection with Listeria monocytogenes, DNA-PKcs-deficient murine macrophages produce reduced levels of IL-18 and are unable to optimally stimulate IFN-γ production by NK cells." (PMID 28362262, 2017). "In summary, our data suggest that genetic variation within the promoter region of IL18 is directly involved in the susceptibility to infection by T. cruzi, which provides novel insight into disease pathophysiology and adds new perspectives to achieve a more effective disease control." (PMID 27027876, 2016). "We investigated in an endemic region of Colombia whether the IL18 gene, which is involved in the immune response to intracellular pathogens like T. cruzi, is related to a higher susceptibility to infection or disease severity." (PMID 27027876, 2016). "In this study, we analyzed the possible role of six IL18 gene variants (rs5744258, rs360722, rs2043055, rs187238, rs1946518 and rs360719), which cover most of the variation within the locus, in the susceptibility to infection by T. cruzi and/or CCC." (PMID 27027876, 2016). "However, D39ΔPLY infection caused a reduced level of capase-1 p10 and the expression of IL-1β and IL-18 was also less elevated in the brains of D39ΔPLY-challeged mice than in D39-challenged mice." (PMID 26683708, 2015). "The last of the parameters which were put in the formula describing the variability of IL-18 was hsCRP, a sensitive marker of inflammation, tissue damage, and infection reflecting the degree of underlying inflammatory response and being a useful measure of immune injury to tissues." (PMID 26669254, 2015). "In addition, we cannot analyze the impact of IL-18 on cause-specific mortality, such as cardiovascular mortality and infection-related mortality." (PMID 24599060, 2014). "Notably, IL-1β and IL-18 secretion are abrogated during infection of NLRP3-deficient (Nlrp3−/−) BMDMs with ΔflaA Lp in both primed and unprimed macrophages." (PMID 23762026, 2013). "In mammals, IL-18 is an inducer of cell-mediated immunity, especially in combination with IL-12, and is primarily associated in Th1 responses to intracellular pathogen infections." (PMID 24358317, 2013). "The interleukin-1 (IL-1) cytokine family, including IL-1α, IL-1β, IL-18, IL-33, IL-36α, IL-36β, and IL-36γ, acts as DAMPs and stimulates sterile inflammation due to tissue necrosis, while also enhancing inflammation associated with tissue damage from infection." (PMID 41214565, 2025).
infection (continued). "However, while our GF and infection experiments argue against a role for commensal or pathogenic bacteria, identifying the triggers and mechanisms that synergize with IL-18 to drive NLRC4V341A-associated pathologies will require further research in this NLRC4V341A mouse model." (PMID 38090573, 2023). "Additionally, IL-18 knockout mice are more susceptible to infection." (PMID 37325809, 2023). "Inflammasomes are cytoplasmic sensors that recognize pathogenic infection, tissue damage or metabolic imbalance, which on activation lead to the maturation and release within a variety of pro-inflammatory factors, namely, interleukin-1β (IL-1β) and interleukin-18 (IL-18)." (PMID 35320937, 2022). "More broadly, interleukin-18 protecting against infection is consistent with it increasing the risk of some auto-immune and atopic conditions, and also accords with the well-established theory that reproduction trades-off against survival, as interleukin-18 also reduced the number of children." (PMID 34911594, 2021). "Interestingly, when infection becomes chronic, hepatic iNKT lymphocytes are progressively reduced in number, conceivably resulting in a loss of sensitivity of iNKT lymphocytes to IL-18 and/or IL-33." (PMID 31507607, 2019). "Also, the maturation and secretion of pro-IL-18 activate the immune defenses and play an important role in the anti-microbial response to infection, and is one of the key inflammasome molecules implicated in the identification of single-stranded RNA (ssRNA) and double-stranded DNA viruses." (PMID 30013955, 2018). "In fecal samples of some IL-18−/− mice that could also be readily colonized by the pathogen, however, commensal enterobacteria could not be detected by direct plating pointing towards additional factors rendering the host susceptible to pathogenic infection." (PMID 27385977, 2016). "Transferred to a potential in-vivo situation, we speculate that, after priming by MSCs, CD56bright NK cells may support inflammation both locally and distant to the site of MSC encounter; for example, upon infection that is associated with the release of IL-12 and IL-18." (PMID 27388156, 2016). "Furthermore, IL-18-deficient mice also demonstrated increased mortality to A/PR8 challenge with increased pathophysiology in the lung for the first 3 days of infection, which included pronounced virus growth with massive infiltration of inflammatory cells and elevated nitric oxide production." (PMID 27283237, 2016). "It will be important, however, for future work to examine whether a lack of IL-18 recapitulates the heightened resistance of MyD88−/− mice, as during infection with T. muris, IL-18 has been shown to promote susceptibility to infection through the inhibition of Th2 cytokines." (PMID 25114104, 2014). "For instance, infection of microglia lines with Theiler's murine encephalomyelitis virus (which causes the development of a chronic-progressive autoimmune demyelinating disease) significantly upregulates the expression of cytokines involved in innate immunity, including IL-18." (PMID 20113500, 2010). "Activation of the IL-18-mediated signaling pathway enhances antimicrobial immunity and reduces infection-induced mortality." (PMID 41783561, 2026). "Cytokine profiling revealed an acute Th1-skewed response, with elevations in CXCL9, CXCL10, IL-27, IFNγ, IL-12, and IL-18 during early infection." (PMID 41636514, 2026). "The NLRP3 inflammasome mediates the maturation of IL-1β and IL-18 primarily in myeloid cells, thereby shaping inflammatory and immunoregulatory responses during infection." (PMID 41753558, 2026). "Taken together, this study shows that colonic ILC2s proliferate and secrete type 2 cytokines in response to CR infection, driven, at least in part, by IL-18." (PMID 40591723, 2025).